STAT3 (signal transducer and activator of transcription 3)
Diseases named in the same sentence as STAT3 in open-access papers (continued):
Sharing a sentence is not in itself a finding about the gene and the disease.
atherosclerosis (continued). "MicroRNA-155-5p promotes progression of atherosclerosis mainly by enhancing inflammatory response during the development of the disease by targeting SOCS1 via the STAT3 and NF-κB signaling pathways." (PMID 34150863, 2021). "The role of STAT3 in the regulation of microRNAs and endothelial dysfunction in atherosclerosis is unclear." (PMID 33456354, 2021). "In fact, it has been also demonstrated that luteolin can suppress also oxLDL-induced inflammation via the inhibition of STAT3 activation, and that it is able to counteract the development and progression of atherosclerosis in ApoE−/− mice with HFD." (PMID 33525692, 2021). "Our research team has published several articles in this field demonstrating that the transcription factors STAT3 and NF-kappaB are involved in atherosclerosis pathogenesis." (PMID 34535081, 2021). "Over-expression of miR-155 promotes the formation of foam cells and aggravates atherosclerosis by targeting SOCS1 via STAT3 and NF-κB signaling pathway." (PMID 34150863, 2021). "Collectively, knockdown of lnc-KCNC3-3:1 alleviates the symptom of atherosclerosis via downregulation of JAK1/STAT3 pathway." (PMID 34540913, 2021). "IL-6 induces the up-regulation of STAT3 in endothelial cells, which is the key factor to activate endothelial dysfunction and induce atherosclerosis." (PMID 33456354, 2021). "All these results suggested that knockdown of lnc-KCNC3-3:1 alleviates development of atherosclerosis via downregulation of JAK1/STAT3 signaling pathway." (PMID 34540913, 2021). "Consistent to in vitro data, the expressions of p-Akt, p-JAK1 and p-STAT3 in tissues of mice were notably increased in atherosclerosis group; however, these phenomena were completely reversed by lnc-KCNC3-3:1 siRNA1." (PMID 34540913, 2021). "In this study, we designed experiments to further investigate the effect of JAK2/STAT3/SOCS3 signaling in rabbit atherosclerosis process." (PMID 32169038, 2020). "We identified the role of upstream regulators such as STAT3 as a transcription factor that is involved in connective tissue disorders and atherosclerosis as it targets many proteins involved in such disorders." (PMID 32753925, 2020). "IL-6, which is highly expressed in atherosclerotic aortas, can directly activate gp130/JAK/STAT3 signaling to exacerbate atherosclerosis." (PMID 32169038, 2020). "Taken together, STAT3 and nAChRα1 blockade attenuates nicotine-induced atherosclerosis by reducing the migration and proliferation of vascular smooth muscle cells and inflammation in macrophages via the Akt/mTOR pathway." (PMID 31612866, 2019). "The inhibition of STAT3 attenuated nicotine-induced atherosclerosis, by reducing the proliferation and migration of vascular smooth muscle cells and inflammation in macrophages." (PMID 31612866, 2019). "In this study, we have revealed the possibility of nicotine accelerating atherosclerosis via nAChRα1/STAT3/Akt/mTOR signaling pathway." (PMID 31612866, 2019). "In this review, we describe the crucial roles of STAT3 in endothelial cell dysfunction, macrophage polarization, inflammation, and immunity during atherosclerosis." (PMID 31588227, 2019). "The inflammatory areas of atherosclerotic plaque lesions show stronger staining of p-STAT3, indicating that the STAT3 activation enhances the progression of atherosclerosis." (PMID 31612866, 2019). "We further revealed that STAT3‐mediated inhibition of PTEN via the induction of miR‐21 in HMECs exposed to AngII is a part of the epigenetic switch linking angiogenesis to atherosclerosis." (PMID 30950039, 2019). "Multiple studies have demonstrated that the signal transducer and activator of transcription 3 (STAT3) plays essential roles in the process of atherosclerosis." (PMID 31588227, 2019). "It has been reported that myocardial infarction-related transcript (MIAT) promotes cell proliferation in an atherosclerosis model by regulating the miR-181b/STAT3 axis." (PMID 31612866, 2019).
atherosclerosis (continued). "Based on this new insight, curcumin also represents a potential therapeutic option for atherosclerosis as an effective STAT3 inhibitor." (PMID 31588227, 2019). "miR-19b inhibits the angiogenesis of endothelial cells by inhibiting STAT3, thus reducing the progression of unstable plaques in patients with atherosclerosis." (PMID 31612866, 2019). "Subsequently, we discuss the pathological roles of STAT3 in atherosclerosis from three independent but related biological processes, endothelial cell dysfunction, macrophage polarization, inflammation, and immunity." (PMID 31588227, 2019). "As we have illustrated above, individuals with abnormal STAT3 activity are prone to atherosclerosis." (PMID 31588227, 2019). "In this study, we profiled the interaction between STAT3 and nAChRα1 and observed that STAT3 inhibition reduces nicotine-accelerated atherosclerosis." (PMID 31612866, 2019). "This study investigated the transcriptional mechanism of STAT3 in nicotine/nAChRα1-induced atherosclerosis." (PMID 31612866, 2019). "This study demonstrated that the atherosclerotic lesion area in the aortic roots in STAT3 knockout mice is significantly reduced compared with that in control mice, suggesting the importance of STAT3 signaling in the progression of atherosclerosis." (PMID 31612866, 2019). "Phosphorylated STAT3 (p-STAT3) has been reported to reduce endothelial cell apoptosis in mouse atherosclerosis models but increase heme-induced endothelial cell apoptosis by up-regulating the target gene matrix metalloproteinase 3 in another study." (PMID 29497350, 2018). "Of all STATs especially STAT1, STAT2, and STAT3 have been recognized as prominent modulators of inflammation, especially in immune and vascular cells during atherosclerosis." (PMID 30283459, 2018). "More importantly, we discovered that OSMR-β deficiency attenuated the development of atherosclerosis and improved plaque stability partially through the inhibition of JAK2/STAT3 signaling." (PMID 28258089, 2017). "Mechanistically, the role of OSMR-β in the development of atherosclerosis is partially mediated through regulation of the JAK2/STAT3 signaling pathway." (PMID 28258089, 2017). "Taken together, these data suggest that the loss of OSMR-β attenuates the development of atherosclerosis, at least partly, via inhibiting the JAK2/STAT3 signal transduction pathway in macrophages." (PMID 28258089, 2017). "The signal transducer and activator of transcription 3 (STAT3) signaling pathway was regarded as a target for the prevention of atherosclerosis or other cardiovascular diseases." (PMID 28097140, 2016). "To confirm the association between PIAS3 and atherosclerosis and assess JAK/STAT3 signalling activation and inflammation during atherosclerosis, we analysed PIAS3, STAT3-Y705, STAT3 and IκBα protein expression in aortas using Western blotting." (PMID 27845432, 2016). "It is known that Janus kinase/signal transducer and activator of transcription 3 (JAK/STAT3) signalling plays an important role in atherosclerosis progression." (PMID 27845432, 2016). "IL-6 is a vascular inflammation indicator and activates JAK/STAT3 signalling to promote atherosclerosis development." (PMID 27845432, 2016). "Previously, for example, we have shown that STAT3 gene delivery, down-stream of interleukin 10 (IL-10), can substitute for IL-10 gene delivery in the inhibition of atherosclerosis in a mouse model." (PMID 25236373, 2014). "Both IL-10 and STAT3 have been shown to inhibit atherosclerosis in an animal model, and both are in the same anti-inflammatory signal transduction pathway, with IL-10 acting through STAT3." (PMID 21915378, 2012). "To elucidate the cellular and molecular mechanisms involved in pravastatin prevention of atherosclerosis, we investigated the impact of pravastatin on STAT3 activity in combating atherosclerosis in apoE-/- mice." (PMID 19330073, 2008).
atherosclerosis (continued). "Transcription activator of transcription (STAT3) is an important member of the signal transduction-activating transcription factor family and plays an important role in atherosclerosis by affecting endothelial cell function, macrophage polarization, inflammation, and immunity." (PMID 40606622, 2025). "Similar to the complement cascade, the JAK2/STAT3 pathway could be a double-edged sword in atherosclerosis." (PMID 39936945, 2025). "It was hypothesized that the dual role of the JAK2/STAT3 pathway in atherosclerosis depends on which isoform of STAT3 is activated: the pro-inflammatory STAT3α or the anti-inflammatory STAT3β." (PMID 39936945, 2025). "Furthermore, IL‐6 functions as a key proinflammatory cytokine, significantly contributing to STAT3‐mediated inflammation in the progression of atherosclerosis." (PMID 40166646, 2025). "Moreover, the identification of JAK/STAT3 as an upstream regulator opens avenues for repurposing existing anti-inflammatory therapies to disrupt mechanosensitive pathways in atherosclerosis." (PMID 40395775, 2025). "LXN deficiency stimulates the JAK1/STAT3/ABC transporter pathway, thereby enhancing the anti-inflammatory and anti-oxidant phenotype, cholesterol efflux, subsequently minimizing foam cell formation and atherosclerosis." (PMID 39424784, 2024). "In addition, LOXL1-AS1 sponges miR-515-5p to inhibit its binding with STAT3, thereby increasing the expression of STAT3, forming a LOXL1-AS1/miR-515-5p/STAT3 positive feedback loop, and promoting cell proliferation and migration in atherosclerosis (AS)." (PMID 38172648, 2024). "However, further results indicate a crucial role of AMPK activity in the regulation of STAT3 signalling in the context of atherosclerosis, thus making the interpretation of STAT3 activity in this context more complex." (PMID 37828508, 2023). "Furthermore, IL-6 and other cytokines are able to activate the JAK2/JAK2-STAT3/STAT3 pathway in fibroblasts and endothelial cells, which facilitates the process of endothelial damage, atheroma formation and atherosclerosis." (PMID 37735399, 2023). "Additionally, miR-7-5p upregulation was found to be cardio-adverse as it was predicted to activate inflammatory response, atherosclerosis, hyperglycemia, cardiovascular disease as well as inhibit angiogenesis and STAT3 and NF-KB pathway." (PMID 37569355, 2023). "aberrant activation of STAT3 has been shown to contribute to the development and progression of atherosclerosis, and signal transducer and activator of transcription 3 (STAT3) have key roles in endothelial cell dysfunction, macrophage polarization, inflammation, and immunity during atherosclerosis." (PMID 36720935, 2023). "We verified 4 genes of them to have a strong correlation with CAD, and IL13RA1 might participate in the inflammation, fibrosis, and cholesterol efflux process of atherosclerosis by regulating JAK1/STAT3 pathway." (PMID 36064568, 2022). "Reduced expression of STAT3 was also observed in plaque samples, but the clinical significance of STAT3 in atherosclerosis remain unclear." (PMID 36456628, 2022). "Their findings suggest that targeting the STAT3/miR-21 axis in conjunction with current atherosclerosis therapies could be effective." (PMID 36250025, 2022). "Additionally, MIAT stimulates cellular proliferation through the miR-181b/STAT3 signaling pathway in an atherosclerosis cell model." (PMID 35053285, 2022). "Accordingly, we propose that IL-1β secreted by inflammatory macrophage induces the functional alterations in macrophage-like VSMCs through downregulating STAT3, and this signaling cascade may play as a main driver in atherosclerosis progression." (PMID 36456628, 2022). "Suppressor of cytokine signaling (SOCS) protein is considered a key physiological regulator of innate and adaptive immunity and SOCS3 plays a protective role in atherosclerosis by inhibiting the STAT3 signaling pathway and suppressing proinflammatory responses." (PMID 36211578, 2022).
atherosclerosis (continued). "ROR upregulates miR-26, NF-κB and JAK1/STAT3 pathways, involved in the atherosclerosis process." (PMID 35407662, 2022). "Moreover, they were all positively associated with RBP4, indicating that RBP4 participates in the formation of atherosclerosis by the JAK2/STAT3 signaling pathway." (PMID 35082965, 2022). "Animal study revealed that knockdown of lnc-KCNC3-3:1 alleviated the symptom of atherosclerosis, and it could inhibit the expressions of p-JAK1, p-STAT3 and p-Akt in tissues of atherosclerosis mice." (PMID 34540913, 2021). "In addition, previous studies have revealed that PI3K/AKT and JAK/STAT3 signaling pathways are involved in atherosclerosis." (PMID 34540913, 2021). "STAT3 inhibition significantly reduces nicotine-induced atherosclerosis." (PMID 34513948, 2021). "Abnormal activation of STAT3 regulates the progression of atherosclerosis through affecting endothelial cells, macrophages, inflammation, etc., and targeted inhibition of STAT3 is consequently considered as a potential treatment strategy for atherosclerosis." (PMID 34688276, 2021). "In addition, BZA effectively downregulated IL-6 via the signal transducer and activator of transcription 3 (STAT3) pathway in an atherosclerosis model." (PMID 34681670, 2021). "JAK/STAT3 overexpression may promote the development of atherosclerosis by facilitating inflammation, proliferation, differentiation and migration of vascular cells." (PMID 32283795, 2020). "From those results, we finally concluded that the inhibition of JAK2/STAT3/SOCS3 signaling may attenuate atherosclerosis in rabbits." (PMID 32169038, 2020). "Taken together, our findings suggest that the inhibition of JAK2/STAT3/SOCS3 signaling may attenuate atherosclerosis in rabbits." (PMID 32169038, 2020). "Taking into account our results, we hypothesized that the high level of plasma lipids, increased the secretion of IL-6, IFN-γ and TNF-α, subsequently activating JAK2/STAT3 to induce and aggravate atherosclerosis." (PMID 32169038, 2020). "Taken together, the inhibition of JAK2/STAT3/SOCS3 signaling pathway may be a novel method for the clinical treatment of artery atherosclerosis." (PMID 32169038, 2020). "Notably, STAT3 is a critical inflammatory mediator in atherosclerosis and inhibition of STAT3 suppressed the ox-LDL induced inflammation in high-fat fed ApoE−/− mice." (PMID 32082313, 2020). "Hyperlipidemia, one of the most important risk factors account for the further development of atherosclerosis, can activate the JAK/STAT signaling of vascular endothelial cells through phosphorylation of JAK2 and subsequently STAT3, leading to the deterioration of atherosclerosis." (PMID 32169038, 2020). "Moreover, we summarize the current inhibitors of STAT3 and explore their implications in atherosclerosis treatments." (PMID 31588227, 2019). "Collectively, this review may be useful for developing future STAT3 inhibitor therapies for atherosclerosis." (PMID 31588227, 2019). "Although, embelin has been reported to inhibit IL6/STAT3 and NF-κB signaling pathways, whether embelin can utilize these properties to prevent the progression of atherosclerosis also needs to be further clarified." (PMID 31635287, 2019). "Then, we present a summary and classification of STAT3 inhibitors, which could offer potential treatment strategies for atherosclerosis." (PMID 31588227, 2019). "Emerging studies reveal that the signal transducer and activator of transcription 3 (STAT3) may play a critical role in all these factors, which indicates that STAT3 might become a new target of atherosclerosis therapies." (PMID 31588227, 2019). "Furthermore, we enumerate some of the problems that have interfered with the development of mature therapies utilizing STAT3 inhibitors to treat atherosclerosis." (PMID 31588227, 2019). "However, the effect of signal transducer and activator of transcription 3 (STAT3)-related inflammatory pathways in nicotine-induced atherosclerosis has been poorly studied." (PMID 31612866, 2019).
atherosclerosis (continued). "Moreover, aberrant STAT3 activation has been shown to contribute to the occurrence and development of atherosclerosis." (PMID 31588227, 2019). "In conclusion, this review may contribute to the application of STAT3 as a novel target of atherosclerosis therapies." (PMID 31588227, 2019). "Oxidative stress and endothelial dysfunction are key steps in the process of atherosclerosis, as we have presented above, which means that STAT3 inhibitors may block the development of atherosclerosis and thus be novel therapeutic options." (PMID 31588227, 2019). "Furthermore, as an important proinflammatory cytokine, IL-6 exerts a profound influence on STAT3-mediated inflammation in atherosclerosis." (PMID 31588227, 2019). "Our results indicated that targeting the STAT3/miR‐21 axis in combination with existing conventional strategies may serve as effective therapies for atherosclerosis." (PMID 30950039, 2019). "In addition to its well-established roles in the nucleus during the progression of atherosclerosis, STAT3 is also present in mitochondria and contributes to the regulation of the electron transport chain (ETC) activity." (PMID 31588227, 2019). "Thus, targeting the STAT3 pathway has become a popular therapeutic approach in the treatment of atherosclerosis." (PMID 31588227, 2019). "The road leading from STAT3 inhibitors to mature therapies for atherosclerosis remains long." (PMID 31612866, 2019). "A previous study revealed the complicated connection between STAT3 and atherosclerosis." (PMID 31612866, 2019). "Collectively, STAT3 inhibitors, which block oxidative stress and vascular dysfunction, could serve as therapeutic agents for atherosclerosis." (PMID 31588227, 2019). "Therefore, we wanted to explore the transcriptional mechanism of STAT3 in nicotine/nAChRα1-induced atherosclerosis." (PMID 31612866, 2019). "In this review, by summarizing the current literature, we highlight the essential roles of STAT3 in atherosclerosis and present STAT3 inhibitors that may become potential treatment agents for atherosclerosis." (PMID 31588227, 2019). "Nicotine enhances the inflammation in atherosclerosis, but the role of the STAT3-related inflammatory pathway in nicotine-induced atherosclerosis is unknown." (PMID 31612866, 2019). "Our findings potentially offer novel therapeutic approaches for nicotine-induced atherosclerosis, but whether smokers can really benefit from nAChRα1 or STAT3 blockade remains to be further studied." (PMID 31612866, 2019). "Inhibitors targeting ND and TAD can mediate the binding of STAT3 dimers and regulate DNA transcription, which may be useful for treating atherosclerosis by suppressing endothelial cell dysfunction, inflammation, and abnormal immune cell differentiation." (PMID 31588227, 2019). "We found that PIAS3, a key negative regulator of JAK/STAT3 signalling, was downregulated in atherosclerotic aortas in mice and that its expression may be inversely correlated with atherosclerosis progression." (PMID 27845432, 2016). "Therefore, it could be hypothesized that AATP exerts anti-inflammatory effects on atherosclerosis by inhibiting the JAK2/STAT3 signaling pathway." (PMID 40647133, 2025). "STAT3 phosphorylation was previously identified as a major inducer of the inflammation-resolving M2 phenotype in macrophages by increasing IL-10 expression and was suggested as a potential mechanism for the protection of ApoE LysMPTP1B(−/−) mice against atherosclerosis." (PMID 37828508, 2023). "Thus, our findings of significantly lower levels of miR-149-5p in stable CAD patients support its active role in the development of atherosclerosis through regulating genes involved in the lipid metabolism as well as suppressing STAT3- or ATF6-mediated inflammation." (PMID 36717592, 2023).